INS (insulin)
Diseases named in the same sentence as INS in open-access papers (continued):
Sharing a sentence is not in itself a finding about the gene and the disease.
diabetes (continued). "The results indicated that eldecalcitol may have a positive effect on those with inadequate insulin production, even while treatment with the drug did not significantly lower the incidence of Type II diabetes among those with pre-diabetes." (PMID 39822434, 2024). "Lastly, the majority of participants with diabetes were not insulin dependent." (PMID 38232087, 2024). "When it comes to insulin, it should be noted that in all cited meta-analyses insulin was shown to be independent predictor of COVID-19 mortality or hospitalization regardless of the age, sex, diabetes duration and gylcemic status." (PMID 38536830, 2024). "Particularly, key proteins of insulin signaling were investigated, i.e., insulin receptor substrate (IRS-1), protein kinase B (PKB/AKT), and glycogen synthase kinase-3 (GSK-3β), which have gained considerable attention from scientists for the treatment of diabetes." (PMID 39795155, 2024). "We can, however, consider the use of weekly basal insulin in other rare forms of diabetes that are independent of T1DM or 2 T2DM and which, over time, will be of increasingly more significant scientific interest since there is no solid evidence in place in the literature on the subject." (PMID 38672255, 2024). "The remainder of his workup was significant for negative diabetes auto-antibodies (islet cell antigen 512, glutamic acid decarboxylase-65, insulin, zinc transporter 8), and a negative Invitae genetic hypoglycemia panel to test for pathogenic gene variants associated with congenital hyperinsulinism." (PMID 39659385, 2024). "In vitro studies have shown that fatty acids impair β-cell insulin signaling and insulin gene transcription while studies by some of our group have demonstrated that β-cell specific deletion of a negative regulator of insulin signaling (ie, PTEN) protects against high fat diet–induced diabetes." (PMID 38578954, 2024). "Although the direct relationship may not be there, insulin intake signifies the severity and uncontrolled nature of diabetes, which in turn might have led to the DR and subsequent worsening of the DR." (PMID 39161485, 2024). "Clinical indicators of better beta cell function and an increased chance of remission are lower HbA1c, the use of fewer medications, no requirement for insulin or sulfonylureas, a shorter known diabetes duration (often self-reported and not always reliable) and younger age." (PMID 38189935, 2024). "These analyses considered patients with type 1 diabetes mellitus (T1DM) in Canada, England/UK, Spain and the USA, T2DM on basal-bolus insulin treatment in Spain, patients with diabetes on intensive insulin treatment in the USA and T1DM and T2DM patients receiving multiple daily insulin in Argentina." (PMID 38709338, 2024). "Diabetes mellitus is a chronic, noncommunicable disease that arises when the body is unable to produce sufficient insulin or fails to effectively utilize the available insulin, leading to a common state of hyperglycemia in the affected individual." (PMID 39950097, 2024). "Interestingly, treatment with a mouse insulin-derived ImotopeTM offered protection from diabetes in a non-obese diabetes mouse model." (PMID 38902652, 2024). "Moreover, jujube products are rich in dietary fiber, which is usually not easily digested by digestive enzymes, and can increase insulin sensitivity by blocking the absorption of glucose, thereby preventing diabetes." (PMID 39065014, 2024). "Recent studies using diabetic animal models have reported that increased insulin sensitivity due to the activation of GLUT4 promotes disease improvement, but it is unclear whether DDW has a direct effect on diabetes, since the influence of various other effects of DDW on the body cannot be ignored." (PMID 39200235, 2024).
diabetes (continued). "Alternatively, given that this study population did not have diabetes at baseline, the main metabolic benefit metformin may offer is lower overall glucose and fasting glucose and the first‐phase glucose clearance and insulin response." (PMID 38346816, 2024). "Although fasting insulin was not significantly elevated, mice receiving HF diet had higher fasting glucose and were heavier than mice receiving SF, similar to prior reports of high fat diet-induced diabetes in C57BL/6 mice." (PMID 39119463, 2024). "Furthermore, 92.27% of patients were diagnosed with Type 2 diabetes mellitus, 73.63% had recorded insulin use, and 60% diagnosed with non-proliferative diabetic retinopathy (NPDR)." (PMID 38890549, 2024). "Moreover, it is important to note that the American Diabetes Association, for the management of GDM, recommends lifestyle changes, including physical activity, as well as the use of insulin when glycemic targets are not achieved." (PMID 39796477, 2024). "When comparing responses to hypoglycaemia using the two different insulin infusion rates of 1.5 and 3.0 mU/kg/min, respectively, in people without diabetes (n = 6), neither the hormonal response nor the symptom scores differed between the two conditions ( p > 0.5)." (PMID 38376580, 2024). "Furthermore, intervention studies conducted in both healthy individuals and patients with diabetes did not identify any significant effects of ASs on factors related to glucose regulation, such as glucose and insulin levels." (PMID 38988858, 2024). "Several factors can influence this relationship, including the presence or absence of diabetes (e.g., T2D), the duration of hyperglycemia, the levels of leptin or adiponectin from the adipose tissue, and the impact of high insulin levels on sex hormone-binding globulin (SHBG)." (PMID 38731059, 2024). "This may be partly attributed to the complexity of treatment algorithms and insulin protocols and fear of hypoglycaemia, especially among general ward staff who are not specialists in diabetes and are often unfamiliar with these guidelines." (PMID 38953925, 2024). "Among those in the insulin group, 42.1% reported being unaware that smoking may be harmful to diabetes compared to 30.2% of those in the non-insulin group (p= 0.02)." (PMID 39587498, 2024). "A strength of the current study is the inclusion of a large number of people with type 1 and long-standing insulin-treated type 2 diabetes and two matched control groups without diabetes, studied under the same experimental conditions, which permitted direct comparisons." (PMID 38376580, 2024). "Disorders in the gut microbiota can reduce insulin sensitivity and energy metabolism by altering the host intestinal mucosal barrier, thus affecting short-chain fatty acid (SCFA) synthesis, bile acid metabolism, and other pathways, ultimately leading to diabetes." (PMID 38660489, 2024). "These themes were: shortage of insulin and management logistics, healthcare providers' knowledge gaps, lack of T1DM care continuity, lack of specialist care, poor healthcare provider-caregiver interactions, shared physical space for diabetes care, long waiting time, and outdated treatment plans." (PMID 38178122, 2024). "Obesity constitutes a chronic hyperinsulinemic state, and when insulin secretion can no longer compensate for insulin resistance, metabolic syndrome and type 2 diabetes mellitus (DM) may develop." (PMID 38159164, 2024). "Unlike other types of diabetes, the dual impairment of alpha and beta cells in type 3c DM alters the interactions between key hormones such as insulin, glucagon, cortisol, catecholamines, and growth hormone, which regulate ketone body production, fatty acid oxidation, and lipolysis." (PMID 39744270, 2024).
diabetes (continued). "Some studies suggested a link between OSA and abnormal glucose metabolism prior to the manifestation of diabetes, and further demonstrated that two pathophysiological processes of OSA (SF and IH) could increase circulating glucose by decreasing insulin sensitivity and reducing glucose effectiveness." (PMID 38762509, 2024). "Diabetes may be classified into two categories: type 1, which requires insulin for management; and type 2, which does not need insulin for management." (PMID 39070354, 2024). "Patients with type 2 diabetes and DR (versus those without DR) were more often on insulin (odds ratio [OR] 3.63, 95% confidence interval [CI] 1.89-7.00), had diabetes for longer (OR 1.04, 95% CI 1.02-1.07), and had higher systolic blood pressure (OR 1.01, 95% CI 1.00-1.02)." (PMID 39420899, 2024). "However, some studies have observed increased CCL4 concentrations in patients in the prediabetic state with a tendency to decrease with insulin intake, which may indicate that CCL4 levels may differ at different stages of diabetes development or severity." (PMID 39769502, 2024). "Type 1 is caused by an autoimmune reaction that causes the body to stop producing insulin, type 2 develops over several years when the body is not able to effectively utilize insulin to maintain blood sugar levels, and gestational diabetes develops in pregnant women who have never had diabetes." (PMID 38611326, 2024). "Notably, dietary niacin supplementation also demonstrated a significant reduction in homeostasis model assessment of insulin resistance (HOMA-IR), fasting blood glucose (in participants without diabetes), and fasting insulin." (PMID 39101008, 2024). "Diabetes impairs the function of the pancreas, especially in type 1 diabetes, where the pancreas is unable to produce insulin, or in type 2 diabetes, the pancreas may not produce enough insulin, or the body may become resistant to its effects." (PMID 39539448, 2024). "Similarly, a longitudinal cross-sectional study on patients recruited from the diabetes prevention trial (PRELLIM) comparing metformin alone to metformin and linagliptin showed favorable outcomes of the combination on insulin sensitivity and pancreatic function." (PMID 39543645, 2024). "Further, HOMA-IR alone may not capture subtle postprandial alterations in glucose and insulin production that occur early in the diabetes progression." (PMID 39261457, 2024). "However, we did not assess the severity of diabetes (e.g., insulin dependency) or new-onset diabetes during follow-up." (PMID 39772140, 2024). "In general, irrespective of glycemic control (HbA1c < 9.0% or ≥ 9.0%), gender (male or female), diabetes onset age (age < 40 or ≥ 40), and BMI (BMI < 30 kg/m2 or ≥ 30 kg/m2), the OAD group exhibited a more substantial reduction in HbA1c levels compared to the insulin group." (PMID 38969701, 2024). "Long-term supplementation with rosehip extract managed to improve the tolerance to glucose, decreased secretion of insulin, and preserved pancreatic beta-cells function in SDT (spontaneously diabetic Torii) rats at the pre-diabetic stage, preventing or delaying the onset of diabetes." (PMID 38765085, 2024). "However, administration of the GHRH analog tesamorelin to type 2 diabetes patients showed no changes in insulin response or diabetes control, despite decreasing cholesterol levels, suggesting that the effect is independent of the GHRH/GH/IGF-1 axis." (PMID 39560873, 2024). "The aim of this study was to compare the efficacy of insulin-loaded, D-α-tocopherol polyethylene glycol succinate (TPGS)-emulsified, chitosan-capped PLGA NPs to that of subcutaneous insulin in an in vivo rat model of diabetes and assess the physical characteristics of synthesized NPs." (PMID 38813352, 2024). "Furthermore, among individuals without diabetes, those who are IR would have higher levels of chemerin and more chemerin activation than those who are insulin sensitive." (PMID 38672278, 2024).
diabetes (continued). "Moreover, it is important to note that reduced insulin and/or IGF-1 signalling noted in other contexts, such as type 2 diabetes mellitus, are highly distinct from inherited reduction in insulin and/or IGF-1 receptor expression, making these difficult to compare." (PMID 39247377, 2024). "Furthermore, patients with diabetes were likely to receive non-recommended 60 mg dose regardless of insulin treatment (DM on insulin: 10.9%; DM not on insulin: 8.7%; no DM: 5.0%)." (PMID 38307927, 2024). "Diabetes mellitus (DM) refers to a group of commonmetabolic disorders in which a person has high blood sugar, either because the pancreas does not produce enough insulin, or becausecells do not respond to the insulin that is produced." (PMID 39132233, 2024). "The crude HRs for those using sodium glucose transporter 2 inhibitors (SGLT2i) were elevated, but the statistical significance vanished with adjustment for age, sex, diabetes duration, and treatment year in both groups (with additional insulin therapy and those without insulin treatment)." (PMID 38403299, 2024). "The results revealed that fenugreek notably improved glycemic control and enhanced insulin sensitivity in individuals with T2DM; however, the studies were inconclusive due to the wide range of doses, from 1 to 100 g of seed or seed extract and participants having differing diabetes status." (PMID 39000103, 2024). "Moreover, MODY is represented by a family history of diabetes, diabetes onset before the age of 25 years, mostly impaired insulin secretion with minimal or no defects in insulin action, and absence of islet autoantibodies." (PMID 39511990, 2024). "Diabetes itself tends to increase the risk of MDD; while short-term antidepressant treatment benefits insulin sensitivity and mitigates depression in non-diabetic patients, long-term effects may show an adverse effect." (PMID 39192909, 2024). "Patients with diabetes have impaired or absent insulin secretion and IR." (PMID 38273418, 2024). "This oral-delivered insulin could potentially increase type 1 diabetes mellitus patient compliance without long-term repeated injection." (PMID 38819767, 2024). "The prespecified clinical question was as follows: “Is insulin Icodec more effective and safer than once-daily basal analogs in improving glycemic parameters of patients with diabetes mellitus who failed to achieve glucose control with non-insulin agents or previous insulin treatment?”." (PMID 39200316, 2024). "After adjusting for other variables; having a history of diabetic complications, duration of diabetes ≥7 years, lack of self-glucose monitoring, lack of regular physical exercise, dyslipidemia, insulin, and the oral hypoglycemic agent was significantly associated with poor glycemic control." (PMID 38962352, 2024). "For participants without diabetes, insulin was not required for injuries <12%TBSA." (PMID 38791089, 2024). "Notably, type 2 diabetes mellitus is a carbohydrate metabolism disorder that occurs due to a major disorder of insulin secretion with or without insulin resistance or relative insulin deficiency and predominant insulin resistance." (PMID 39559676, 2024). "Elevated blood glucose and insulin have been reported in obese patients with or without diabetes." (PMID 39199499, 2024). "Participants who reported a diabetes diagnosis were asked about disease duration (<10 years vs ≥10 years), if they followed a diet for diabetes (Yes vs No), and treatment received (unknown, oral hypoglycemic, insulin, or oral hypoglycemic/insulin combination)." (PMID 39058533, 2024). "Additionally, the prognosis for HF patients without diabetes is likely to be worse than that for patients with normal blood glucose and insulin levels." (PMID 38678275, 2024).
diabetes (continued). "It has been noted that resistance to insulin depends on vitamin D levels, showing a positive correlation between insulin sensitivity and levels of vitamin D. Overall, VDD is reported in 70–90% of individuals with diabetes, but only a handful of studies have been done in Saudi Arabia in this regard." (PMID 38394491, 2024). "However, this surgery should be avoided whenever possible, because it will lead to insulin-requiring diabetes starting from childhood, without a clear preventing effect on the cognitive outcome." (PMID 38952388, 2024). "While the study excludes minors and acknowledges that type 2 diabetes significantly predominates among adult diabetes cases, the absence of data on insulin-related antibodies in NHANES constrains our ability to definitively distinguish between type 1 and type 2 diabetes." (PMID 38789523, 2024). "Although studies of ABHD1 in diabetes and its complications are rare, research has found that inhibitors of ABHD6 in the same family may play a role in the treatment of type 2 diabetes, insulin resistance, and metabolic syndrome by promoting insulin secretion." (PMID 39619568, 2024). "Notably, Klf11 null mice do not develop diabetes but still show decreased circulating insulin, abnormal glucose tolerance, and increased insulin sensitivity in peripheral organs." (PMID 39462409, 2024). "However, owing to its solid binding affinity to insulin (unlike IGFBP 1–6), IGFBP7 can influence insulin’s physiological activity, possibly contributing to insulin resistance, facilitating the progression of diabetes, as demonstrated by several studies." (PMID 39335666, 2024). "Without potassium, one cannot secrete insulin, leading to hyperglycemia and worsening diabetes." (PMID 38333496, 2024). "Compared with participants without diabetes, those with diabetes had a higher age, men-to-women ratio, high BMI proportion, non-Hispanic black race proportion, and circulating levels of Pb, glucose, insulin, and HbA1c, along with higher HOMA-IR." (PMID 39853009, 2024). "Also, 37 (27.6%) had diabetes, with a higher prevalence in DISH (39.5%) and DDD (29.0%) groups, compared to axSpA 7.4% (p = 0.012), also reflected in higher levels of HbA1c and treatment with oral antidiabetics and insulin." (PMID 39097721, 2024). "Similarly, data on acute complications related to diabetes will be collected at baseline, such as hypoglycemia and lactic acidosis or ketoacidosis; and current diabetes treatments, including non-drug therapy, oral hypoglycemic drugs, and insulin therapy." (PMID 37480092, 2023). "However, we stigmatize that, in the previous PREFER in AF analysis, the predictive role of insulin-requiring diabetes on outcomes was independent of diabetes duration." (PMID 35976428, 2023). "Amongst pts with diagnosed diabetes mellitus, the mOS was identical irrespective of whether they were treated with insulin or not." (PMID 37297851, 2023). "The guidelines considered in the current review article may, however, not entirely reflect the insulin usage protocols/practices followed across all countries and individual institutions/hospitals across the globe in the management of type 2 diabetes mellitus." (PMID 36650625, 2023). "Furthermore, 204 (33.3%) correctly identified diabetes as a condition where the body does not respond to insulin, and 492 (80.2%) correctly classified it as a noncontagious disease." (PMID 37772210, 2023). "DKA may be the first presentation of previously unknown diabetes mellitus or may be a nonrecurrent or recurrent event in those with established diabetes mellitus due to either omission of insulin and/or intercurrent stressors." (PMID 37720598, 2023). "Obese insulin-resistant subjects with or without diabetes show impaired platelet responsiveness to the inhibitory effects of insulin, thus suggesting that each strategy useful in reducing insulin-resistance can also improve the vascular effects of insulin including its antiplatelet effects." (PMID 37627603, 2023).